HTT (huntingtin)
Diseases named in the same sentence as HTT in open-access papers (continued):
Sharing a sentence is not in itself a finding about the gene and the disease.
Huntington disease (continued). "Huntington’s disease (HD) is caused by a polyglutamine expansion in the N-terminal region of huntingtin (HTT)." (PMID 27203582, 2016). "Huntington’s disease (HD) is a neurodegenerative disorder caused by an abnormal expansion of polyglutamine repeats in the N-terminal of huntingtin." (PMID 27377031, 2016). "Huntington’s disease (HD) is a genetic disease caused by a CAG trinucleotide repeat expansion encoding a polyglutamine tract in the huntingtin (HTT) protein, ultimately leading to neuronal loss and consequent cognitive decline and death." (PMID 26428929, 2016). "Mutant Huntingtin (mtHtt) causes neurodegeneration in Huntington's disease (HD) by evoking defects in the mitochondria, but the underlying mechanisms remains elusive." (PMID 27561680, 2016). "Huntington's disease (HD) is a neurodegenerative disorder caused by accumulation of CAG expansions in the huntingtin (HTT) gene." (PMID 27003755, 2016). "Later it was named after him as Huntington's disease (HD) and in early 1990s the mutant gene Huntingtin (HTT) was discovered to be the cause of the disease." (PMID 27924190, 2016). "Expansion of the polyglutamine (polyQ) tract in the huntingtin (Htt) protein causes Huntington’s disease (HD), a fatal inherited movement disorder linked to neurodegeneration in the striatum and cortex." (PMID 27658206, 2016). "Expansion of the polyglutamine (polyQ) track of the Huntingtin (HTT) protein above 36 is associated with a sharply enhanced risk of Huntington’s disease (HD)." (PMID 27271685, 2016). "Huntington’s disease (HD) is a fatal neurodegenerative disease caused by an expanded polyglutamine tract in the huntingtin gene." (PMID 25941073, 2016). "Huntington's disease (HD) is a progressive neurodegenerative disorder caused by a polyglutamine-repeat expansion in the huntingtin protein." (PMID 27611938, 2016). "Huntington’s disease is a neurodegenerative disorder characterised primarily by motor abnormalities, and is caused by an expanded polyglutamine repeat in the huntingtin protein." (PMID 26660732, 2015). "Mutant huntingtin aggregation is highly associated with the pathogenesis of Huntington’s disease, an adult-onset autosomal dominant disorder, which leads to a loss of motor control and decline in cognitive function." (PMID 25699594, 2015). "Induction of autophagy has been shown in a Huntington disease model in response to the pathogenic mutant version of huntingtin, and induction of mRNA and protein p62 expression have been demonstrated upon expression of poly-Q expanded huntingtin." (PMID 25888134, 2015). "Mutant huntingtin (mHtt) aggregation in the nucleus is the most readily apparent phenotype and cause of neuronal death in Huntington’s disease (HD)." (PMID 26586297, 2015). "Huntington’s disease (HD) is caused by a trinucleotide CAG repeat in thehuntingtin gene (HTT) that results in expression of a polyglutamine-expandedmutant huntingtin protein (mHTT)." (PMID 26664998, 2015). "Huntington’s disease is caused by the polyglutamine-repeated protein aggregates from aberrant ubiquitination of huntingtin protein by TRAF6." (PMID 25734985, 2015). "Expression of mutant huntingtin (htt) protein has been shown to cause metabolic imbalance in animal models of Huntington disease (HD)." (PMID 26419281, 2015). "Huntingtin (HTT), the protein that is mutated in Huntington disease, acts as a scaffold for molecular motors and promotes microtubule-based dynamics." (PMID 25942483, 2015). "Huntington’s disease (HD) is a neurodegenerative disorder in which the mutation results in an extra-long tract of glutamines that causes the huntingtin protein to aggregate." (PMID 25748626, 2015). "Huntington’s disease (HD) is an autosomal dominant neurodegenerative disorder caused by a CAG trinucleotide repeat expansion in the huntingtin gene." (PMID 25859666, 2015).
Huntington disease (continued). "Huntingtin (HTT), the protein mutated in Huntington disease, modulates RAB11A activity and also regulates the microtubule-based vesicular trafficking in neurons." (PMID 25942483, 2015). "The expanded trinucleotide(CAG) tract in exon 1 of the huntingtin gene is the major cause of Huntington’s disease(HD) and particularly, CAG repeats beyond 35 in number are known to increase disease risk." (PMID 25723488, 2015). "Huntington disease (HD) is a devastating autosomal dominant neurodegenerative disease caused by the expansion of polyglutamine (polyQ) residues (>36Q) in exon 1 of the huntingtin (HTT or IT15) gene." (PMID 25966278, 2015). "Huntington’s disease is a neurodegenerative disorder caused by toxic insertions of polyglutamine residues in the Huntingtin protein and characterized by progressive deterioration of cognitive and motor functions." (PMID 25761110, 2015). "It has been previously reported that N-terminus of mutant huntingtin (product of the 1st exon) is sufficient to cause a Huntington's disease (HD) pathological phenotype." (PMID 26635623, 2015). "Huntington’s disease is a polyglutamine repeat disorder, dominantly inherited and caused by abnormal expansions of long glutamine sequences found in huntingtin." (PMID 26053162, 2015). "Recently, HDAC4 was found to be associated with aggregate-prone mutant Huntington's disease–associated products of the huntingtin gene (HTT) that have long polyglutamine stretches." (PMID 26540094, 2015). "Huntington’s disease (HD) is an autosomal dominant neurodegenerative disorder caused by a CAG expansion within the first exon of the HTT gene, which gives rise to an expanded polyglutamine tract in the huntingtin protein." (PMID 26660732, 2015). "Huntington’s disease (HD) is a fully penetrant autosomal dominant neurodegenerative disorder caused by an expansion of a CAG repeat in the huntingtin gene." (PMID 25659157, 2015). "The study identified reduced expression of SIRT3 because of mutant protein huntingtin (Htt), which causes Huntington’s disease." (PMID 25907989, 2015). "Huntington’s disease is the result of a long polyglutamine tract in the gene encoding huntingtin protein, which in turn causes a large number of cellular changes and ultimately results in neurodegeneration of striatal neurons." (PMID 26691307, 2015). "Huntington’s disease (HD) is an inherited neurodegenerative disorder caused by the expansion of CAG repeats in exon 1 of the huntingtin (HTT) gene." (PMID 25992839, 2015). "We identify functional hsiRNAs targeting the mRNA of huntingtin, the mutation of which is responsible for Huntington's disease, and show that direct uptake in neurons induces potent and specific silencing in vitro." (PMID 26623938, 2015). "Huntington’s Disease (HD) is a devastating neurodegenerative disorder that is caused by an expanded CAG trinucleotide repeat in the Huntingtin (HTT) gene." (PMID 26636579, 2015). "We investigated the effects of PI5P4K2s knockdown and overexpression on the levels of diverse autophagic substrates, including the ubiquitin-binding adaptor protein p62 and a mutant form of huntingtin associated with Huntington’s disease (EGFP-httQ74)." (PMID 25578879, 2015). "As a model for our studies, we silenced the huntingtin (Htt) gene, the causative gene in Huntington's disease (HD)." (PMID 26623938, 2015). "Huntington’s disease is a fatal neurodegenerative condition caused by a CAG repeat expansion in the huntingtin gene." (PMID 26529236, 2015). "Huntington’s disease is caused by an abnormal CAG repeat expansion within exon 1 of the human huntingtin gene (HTT) encoding the huntingtin (HTT) protein." (PMID 25953777, 2015). "HDAC4 associates with the aggregation-prone mutant huntingtin protein (mHTT) that causes Huntington's disease, and colocalizes with it in cytosolic inclusions." (PMID 26540094, 2015).
Huntington disease (continued). "Huntington’s disease (HD) is an inherited progressive neurodegenerative disorder caused by an expanded CAG repeat in exon 1 of the huntingtin gene (HTT)." (PMID 25719447, 2015). "Huntington's disease (HD) is an inherited neurodegenerative disorder caused by a CAG repeat encoding a polyglutamine tract within the amino-terminus of the huntingtin (HTT) protein." (PMID 25859666, 2015). "Huntington’s Disease (HD) is caused by a mutant huntingtin protein (htt) protein that contains a polyglutamine tract encoded by a trinucleotide CAG repeat in the first exon of the HTT gene." (PMID 26496077, 2015). "Huntington disease (HD) is caused by expansion of a CAG repeat within the first exon of the huntingtin gene (4p16.3)." (PMID 25294428, 2015). "Huntington's disease (HD) is caused by mutational Huntingtin gene that occurred in the short arm of chromosome 4 p16.3." (PMID 26779531, 2015). "Huntington’s disease (HD) is a dominantly inherited neurodegenerative disease caused by an expansion of CAG repeats located in first exon of the Huntingtin (HTT) gene." (PMID 26376480, 2015). "Huntington's disease (HD) is a genetic neurological disorder caused by a CAG expansion in the gene encoding the huntingtin (HTT) protein." (PMID 26589247, 2015). "Huntington’s disease (HD) is a devastating neurological disorder that is caused by an expansion of the poly-Q tract in exon 1 of the Huntingtin gene (HTT)." (PMID 26010866, 2015). "Huntington disease (HD) is a fatal neurodegenerative disorder caused by an expanded CAG repeat in the huntingtin gene." (PMID 25659157, 2015). "Huntington’s disease (HD) is a neurodegenerative disorder caused by the huntingtin (HTT) gene with expanded CAG repeats." (PMID 25992839, 2015). "Huntington's disease (HD) is a fatal neurodegenerative disorder caused by aberrant expansion of CAG repeat in the huntingtin gene." (PMID 25611391, 2015). "Huntington disease is caused by expansion of a CAG repeat in the huntingtin gene that is translated into an elongated polyglutamine stretch within the N-terminal domain of the huntingtin protein." (PMID 25294428, 2015). "Huntington’s disease (HD) is neurodegenerative disorder in which the mutation results in the increased length of a tract of glutamines that causes the huntingtin protein (HTT) to aggregate." (PMID 25748626, 2015). "Huntington’s disease (HD) is a neurodegenerative illness, where selective neuronal loss in the brain caused by expression of mutant huntingtin protein leads to motor dysfunction and cognitive decline in addition to peripheral metabolic changes." (PMID 26064782, 2015). "Huntington's disease (HD) is a neurodegenerative disorder for which the mutation results in an extra-long tract of glutamines that causes the huntingtin protein to aggregate." (PMID 25101683, 2014). "Huntington disease (HD) is a fatal autosomal dominant neurodegenerative disorder caused by an increased number of CAG repeats in the HTT gene coding for huntingtin." (PMID 25271153, 2014). "As the expanded allele in Huntington disease is dominant, patients are nearly always heterozygous and therefore possess both normal and expanded huntingtin." (PMID 24961702, 2014). "In this paper, the expression of theN-terminal fragment of mutated huntingtin (Htt138Q-1exon) is shown to be enoughto provide an actual model for Huntington’s disease." (PMID 25558393, 2014). "Huntington's disease (HD) is a fatal neurodegenerative disorder caused by a polyglutamine expansion in the huntingtin (HTT) protein." (PMID 24804153, 2014). "Huntington's disease is a fatal neurodegenerative disease caused by polyglutamine-expansion in huntingtin (HTT)." (PMID 25332397, 2014). "Huntington’s disease is a neurodegenerative disorder caused by mutations in the CAG tract of huntingtin." (PMID 24558637, 2014). "Huntington's disease (HD) is an inherited neurodegenerative disorder caused by the expansion of a polyglutamine (polyQ) stretch within the huntingtin protein (HTT)." (PMID 25101683, 2014).
Huntington disease (continued). "Aggregation of a polyglutamine-expanded Huntingtin, causative of Huntington’s disease, appears unaltered by COMMD1." (PMID 24691167, 2014). "Huntington’s disease (HD) is a hereditary autosomal neurodegenerative disorder caused by an expanded Cytosine-Adenine-Guanine (CAG) repeat in the HTT gene." (PMID 25227988, 2014). "Huntington disease is caused by the expansion of a trinucleotide repeat within the Huntingtin (HTT) gene, leading to the formation of an extended polyglutamine stretch at the N-terminal of the protein Huntingtonin." (PMID 25107477, 2014). "HYPK (Huntingtin Yeast Partner K) was originally identified by yeast two-hybrid assay as an interactor of Huntingtin, the protein mutated in Huntington's disease." (PMID 24465598, 2014). "Huntington's disease (HD) is neurodegenerative disorder caused by the expansion of polyglutamine stretch within the huntingtin protein (HTT)." (PMID 25339908, 2014). "Huntington’s disease (HD) is an inherited neurodegenerative disease caused by expansion of CAG trinucleotide repeats secondary to mutation in the huntingtin gene on chromosome 4p16.3." (PMID 25053996, 2014). "Huntington's Disease (HD) is a neurodegenerative disorder that is caused by abnormal expansion of a polyglutamine tract in huntingtin (htt) protein." (PMID 24475300, 2014). "Huntington’s disease (HD) is caused by a mutation that expands the number of trinucleotides CAG repeats in a gene leading to an expansion of polyglutamine stretch in huntingtin, the encoded protein." (PMID 25054562, 2014). "EIF2α phosphorylation was elevated in a striatal cell line stably expressing pathogenic huntingtin, as well as in brain sections of Huntington’s disease model mice." (PMID 24594939, 2014). "Huntington’s disease (HD) is an autosomal dominant neurodegenerative disorder caused by the expansion of a CAG triplet repeat in exon 1 of the huntingtin (HTT) gene, translated into a polyglutamine tract in the HTT protein." (PMID 24581271, 2014). "Considerable evidence supports the idea that huntingtin aggregation causes neuronal death in Huntington disease." (PMID 24961702, 2014). "A hallmark of Huntington’s disease is the pronounced sensitivity of striatal neurons to polyglutamine-expanded huntingtin expression." (PMID 24594939, 2014). "Huntington's disease is an autosomal dominant neurodegenerative disorder caused by the expansion of CAG repeats in the huntingtin gene." (PMID 24587280, 2014). "The expansion of a CAG trinucleotide repeat in the huntingtin gene, which produces huntingtin protein with an expanded polyglutamine tract, is the cause of Huntington's disease (HD)." (PMID 24816435, 2014). "Huntington disease (HD) is a fatal autosomal dominant neurodegenerative disorder caused by a CAG repeat expansion in the gene (HTT) encoding the huntingtin protein." (PMID 24728353, 2014). "In Huntington’s disease (HD), a neurodegenerative disease caused by a tri-nucleotide repeat expansion in the huntingtin gene, extensive transcriptional dysregulation has been reported." (PMID 25358814, 2014). "Huntington's disease (HD) is a hereditary neurodegenerative disorder caused by the expansion of a polyglutamine stretch within the huntingtin protein (HTT)." (PMID 25339908, 2014). "To this end, we have characterized a set of novel antibodies and employed a unique assay platform for the detection of the huntingtin protein (HTT), the causative agent in Huntington's disease (HD)." (PMID 24816435, 2014). "Huntington’s disease (HD) is a devastating, genetic neurodegenerative disease caused by a tri-nucleotide expansion in exon 1 of the huntingtin gene." (PMID 24503862, 2014). "Huntington disease (HD) is a fatal neurodegenerative disorder caused by a CAG repeat expansion in the gene (HTT) encoding the huntingtin protein (HTT)." (PMID 24728353, 2014).
Huntington disease (continued). "Huntington's disease (HD) is neurodegenerative disorder for which the mutation results in an extra-long tract of glutamines that causes the huntingtin protein to aggregate." (PMID 25268775, 2014). "Huntington’s disease (HD) is an autosomal dominant neurodegenerative disorder caused by a mutation in the gene encoding the huntingtin (Htt) protein." (PMID 25147502, 2014). "Huntington’s Disease (HD) is a progressive neurodegenerative disorder with a single causal mutation in the Huntingtin (HTT) gene." (PMID 24929669, 2014). "Huntington’s disease (HD) is a genetically inherited neurodegenerative disorder caused by a mutation to the huntingtin (HTT) gene." (PMID 24961705, 2014). "Huntington’s disease (HD) is a devastating neurodegenerative disorder caused by an expanded CAG repeat in the huntingtin (HTT) gene." (PMID 25271967, 2014). "Huntington's disease is a neurodegenerative disorder caused by an expansion of CAG repeats in the huntingtin gene which produces widespread neuronal and glial pathology." (PMID 24069174, 2013). "Huntington's disease is an autosomal dominant inherited disorder caused by an elongated CAG repeat expansion in the huntingtin (HTT) gene." (PMID 24133413, 2013). "The cause of Huntington disease (HD) is a polyglutamine repeat expansion of more than 36 units in the huntingtin protein, which is inversely correlated with the age at onset of the disease." (PMID 23894380, 2013). "Huntington disease (HD) is a hereditary neurodegenerative disorder caused by a CAG repeat extension in the coding region of the huntingtin gene, leading to striatal atrophy which later expands to the cerebral cortex and other subcortical brain regions." (PMID 24303051, 2013). "In particular, several fly strains have been generated to model Huntington’s disease (HD), a dominantly inherited neurodegenerative disorder caused by an abnormal polyglutamine (polyQ) expansion in the huntingtin (HTT) protein." (PMID 23555909, 2013). "Huntington’s disease (HD) is a neurodegenerative disorder primarily caused by a mutation in the gene encoding Huntingtin, which results in the production of a mutated protein (mHtt)." (PMID 23799154, 2013). "Huntington’s disease (HD) is an autosomal dominant genetic disorder caused by abnormal CAG expansion in exon 1 of the huntingtin gene (mhtt) and pathologically characterized by progressive degeneration of striatal and cortical neurons." (PMID 23967334, 2013). "Huntington’s disease (HD) is an inherited neurodegenerative disorder caused by a CAG repeat expansion in the huntingtin (HTT) gene." (PMID 24459609, 2013). "Huntington's disease (HD) is an inherited neurodegenerative disorder caused by mutations in the Huntingtin (HTT) protein which result in expanded Poly-glutamine (PolyQ, CAGn) repeats that cause aggregation-prone amyloidosis." (PMID 24367279, 2013). "Huntington’s disease (HD) is an autosomal dominant neurodegenerative disorder caused by an expanded CAG repeat in the coding region of the huntingtin gene." (PMID 24040016, 2013). "Huntington’s disease (HD) is a fatal neurodegenerative disorder caused by an expanded polyglutamine repeat in the huntingtin protein." (PMID 24376631, 2013). "In Huntington disease (HD), polyglutamine expansion in the huntingtin protein causes specific neuronal death." (PMID 23300147, 2013). "Huntington's disease (HD) is an autosomal dominant progressive neurodegenerative disorder caused by poly-Q expansions in the Huntingtin protein." (PMID 24364034, 2013). "Huntington's disease (HD) is a late-onset neurodegenerative disorder caused by protein-folding defects in the huntingtin protein." (PMID 24302884, 2013). "Huntington's disease (HD) is caused by huntingtin protein carrying an expanded number of CAG repeats, whilst tauopathy, synucleinopathy and expanded tri-nucleotide-repeats are also associated with other neurodegenerative diseases." (PMID 23797088, 2013).